SOD1 (superoxide dismutase 1)
Diseases named in the same sentence as SOD1 in open-access papers (continued):
Sharing a sentence is not in itself a finding about the gene and the disease.
age-related macular degeneration (10 papers, 2013 to 2023). Age-related loss of vision in the central portion of the retina (macula), secondary to retinal degeneration. "SOD1-deficient mice (Sod1−/− mice) exhibit high levels of oxidative stress when compared to wild-type mice, and have been shown to display ocular defects, including age-related macular degeneration and lacrimal gland dysfunction, as observed in humans." (PMID 33233466, 2020). "Our previous studies showed that mice deficient in Cu, Zn superoxide dismutase (SOD1) to be a suitable animal model for the study of human age related diseases, as the mice display all the features of age related macular degeneration and lacrimal gland dysfunction observed in humans." (PMID 25036096, 2014). "ALS and frontotemporal dementia are understood to be on a continuum, and SOD1 null mice develop retinopathies similar to age-related macular degeneration (AMD) and glaucoma, presumably due to increased oxidative stress." (PMID 29064456, 2017). "Twelve-month-old SOD1−/− mice, which are used as an animal model of age-related macular degeneration, displayed increased CML formation in Bruch’s membrane and in the pigment epithelium compared to age-matched, wild-type mice." (PMID 26404251, 2015). "This metric was validated in a phantom and applied in a longitudinal study of superoxide dismutase 1 knockout (SOD1−/−) mice, a model for wet and dry age-related macular degeneration." (PMID 36259678, 2022).
amyloidosis (10 papers, 2010 to 2023). A disorder characterized by the localized or diffuse accumulation of amyloid protein in various anatomic sites. "It is thus conceivable that downregulation and therefore loss of CD39 function, as observed in the spinal cord of ALS subjects and in transcriptomic data from SOD1 mutant mice and murine amyloidosis models, could have detrimental consequences." (PMID 34054698, 2021). "This implies, however, that cellular conditions or genetic changes that favour multimers dissociation would also favour non-functional interactions, as it occurs in the case of human transthyretin or superoxide dismutase 1, whose dissociation leads to their aggregation and the onset of amyloidosis." (PMID 31398930, 2019). "Whether fALS with SOD1 mutations is a typical amyloidosis is not clear." (PMID 20399791, 2010). "Conversely, the dramatically low expression of PGC-1α at 12 months in AD neurons, when we first observe hippocampal amyloid deposits (not shown), is concomitant with the lower levels of SOD1, SOD2 and, particularly, GPX1, compared to WT." (PMID 23374228, 2013). "Interestingly, aggregation pathways involving dissociation of oligomers are well-established for several proteins undergoing pathological β-aggregation, such as transthyretin and SOD1, respectively involved in familial amyloidotic polyneuropathy (FAP) and ALS, two amyloid-forming diseases." (PMID 24098542, 2013).
bladder cancer (10 papers, 1983 to 2025). "Our results clearly showed that PPM-18 remarkably promoted ROS production in bladder cancer cells, in accompany with the altered expression of antioxidant proteins, such as SOD1 and catalase." (PMID 34305598, 2021). "Similarly, WFA upregulates the mRNA expression of antioxidant genes (NFE2L2, CAT, SOD1, TXN, GSR, NQO1, and HMOX1) in bladder cancer cells associated with oxidative stress generation." (PMID 34209212, 2021).
cutaneous leishmaniasis (10 papers, 2010 to 2022). Leishmaniasis affecting the skin. "The data obtained in this study confirm and extend our previous finding of an IFN-I/Sod1 axis, linked to increased parasite burden and therapeutic failure in both localized cutaneous leishmaniasis and DCL." (PMID 28959260, 2017). "For example, L. amazonensis (belonging to L. mexicana complex which causes cutaneous leishmaniasis) suppresses NO production by repressing the iNOS expression via the NF-kB transcription factor and reduces ROS accumulation by inducing SOD-1 in human and mouse cells." (PMID 27978534, 2016). "In contrast, the enzyme Sod1, which was reported to impair macrophage-related parasite killing in cutaneous Leishmaniasis, showed lower expression in ileal macrophages." (PMID 31916932, 2020). "Pronounced SOD-1 expression levels were also detected in biopsies from New World cutaneous leishmaniasis patients." (PMID 28690662, 2017). "More recently, SOD-1 has been found to play a deleterious role in cutaneous leishmaniasis, as the interferon-beta inhibition of leishmanicidal activity was mimicked by SOD-1 and antagonized by either pharmacological or small interfering RNA-mediated inhibition of SOD-1." (PMID 20386593, 2010). "The SOD1-inhibitor diethyldithiocarbamate (DETC) kills intracellular parasites in vitro and in vivo in a murine model of cutaneous leishmaniasis." (PMID 31297344, 2019).
keratoconus (10 papers, 2011 to 2025). A degenerative, structural disorder of the eye, characterized by a cone-shaped protrusion of the cornea. "Donor genomic DNA extracted from blood samples was screened for 5'UTR, exonic LOX, and SOD1 variants in a subset of 26 patients presenting with advanced keratoconus (KISA > 1000% and I–S > 2.0) by Sanger sequencing." (PMID 32308947, 2020). "A 7-base SOD1 deletion (IVS2 + 50del7bp) previously associated with keratoconus was screened in 140 patients presenting classical keratoconus by gel fragment analysis, and positive samples were sequenced for confirmation." (PMID 32308947, 2020). "This is particularly important for SOD1, as the variant previously associated with keratoconus was a 7bp intronic deletion, outside of the capture regions in this study." (PMID 29924831, 2018). "The presence of the c.169+50delTAAACAG change, the unique SOD1 variant that was found associated to the keratoconus, was evaluated in the patients in this study." (PMID 21976959, 2011). "Thus, a possible causative role of SOD1 in the pathogenesis of keratoconus needs to be further studied." (PMID 21976959, 2011). "SOD1 (OMIM: 147450) is located on chromosome 21 while Trisomy 21 is notably at high risk for keratoconus; thus, a role in the increased oxidative damage found in keratoconic corneas could not be discarded." (PMID 21976959, 2011). "In this study, we performed linkage analysis for six known chromosomal loci as well as a mutation detection screen in VSX1 and SOD1 in 112 affected, 52 unaffected family members and 100 normal individuals as controls in a group of Iranian patients with keratoconus." (PMID 22171159, 2011). "Mutational analysis of VSX1, SPARC, and SOD1 in 302 subjects affected by keratoconus." (PMID 21976959, 2011). "In this study, we report the mutational analysis results for VSX1, LOX, SPARC, TIMP3, and SOD1, performed in a large cohort of Italian subjects affected by sporadic and familial keratoconus." (PMID 21976959, 2011). "In contrast, the genes VSX1 and SOD1, were initially proposed to play a role in keratoconus due to the identification of sequence variants in keratoconus patients that were absent in controls." (PMID 29924831, 2018). "Also, VSX1, SOD1, and LOX genes are associated with keratoconus in some studies." (PMID 40002778, 2025). "In some patients, their genetic predisposition to keratoconus, that is, polymorphisms in COL4A3 and COL4A4 genes, encoding components of type IV collagen, a major corneal structural protein, and/or mutation in the superoxide dismutase 1 gene may accelerate the corneal changes." (PMID 26881021, 2016). "Other candidate genes including SOD1, ZEB1, TGFB1, FLG, interleukin, and collagen may have a role to play in the pathogenesis of keratoconus and need further elucidations." (PMID 25254113, 2014). "Additionally, SOD1 deletion was detected in one patient presenting with severe keratoconus, not in control samples." (PMID 32308947, 2020).
lymphoma (10 papers, 2010 to 2025). A malignant (clonal) proliferation of B- lymphocytes or T- lymphocytes which involves the lymph nodes, bone marrow and/or extranodal sites. "To further validate these in vitro data, we analyzed the expression of Mcl-1 and SOD1 in a panel of patient-derived lymphoma biopsies." (PMID 40707672, 2025). "Dietary restriction resulted in a 30% increase in the lifespan of Sod1-/- mice compared with controls, a significant reduction in oxidative damage, and a reduction in the incidence of lymphomas." (PMID 37759977, 2023). "The main finding of this study is that by reproducing in vitro a condition of in vivo hyperCHO, lymphoma lymphoblastic cells overexpressed genes for antioxidant proteins (SOD1, SOD2, CCS, GSR, GSS and CAT) with the only exception of GRX2." (PMID 26754536, 2016). "Indeed, analysis of lysates from 13 lymphoma patients revealed a significant inverse correlation between Mcl-1 and SOD1 protein levels in vivo, validated by Pearson correlation analysis." (PMID 40707672, 2025). "Finally, in an in vivo setting, we observed a significant inverse correlation between T163pMcl-1 and SOD1 protein expression levels in a range of 13 lymphoma patient samples." (PMID 40707672, 2025).
pneumonia (10 papers, 2021 to 2025). An acute, acute and chronic, or chronic inflammation focally or diffusely affecting the lung parenchyma, caused by an infection in one or both of the lungs (by bacteria, viruses, fungi, or mycoplasma.). "Since mice with a Sod1-deficiency are anemic and WBCs play pivotal roles in the pathogenesis of pneumonia, we evaluated the abundance of blood cells in the DKO mice on days 0, 4, 7, and 10 following Asc withdrawal and compared these with those of the WT mice." (PMID 40616948, 2025). "In our opinion, this is the first study to identify SNPs in antioxidant (SOD1, CAT, GPX1, NOS, HMOX1, and NQO1) and immunological (IL-1α, IL1B, IL6, TNF-α, IL10, LFA-1, CR2, IL17, IL13, DEFB123, SCART1, and ICAM1) genes as potential suspects for pneumonia resistance/susceptibility in Barki ewes." (PMID 40221769, 2025). "Conversely, the expression levels of IL10, SOD1, CAT, GPX1, and NQO1 were significantly lower in the pneumonia group than in the healthy control group." (PMID 40221769, 2025).
tauopathies (10 papers, 2010 to 2024). "Mouse neurodegenerative datasets (n = 9) included ALS (various SOD1 mutants, n = 3) and AD models of both brain β-amyloidosis (n = 5) (APPswe/PSEN1deltaE9 n = 3 and PS2APP n = 2), and tauopathy (P301S-MAPT, n = 1)." (PMID 32736565, 2020).
uveitis (10 papers, 2011 to 2023). An inflammatory process affecting a part of or the entire uvea. "Their results showed that applying nano-SOD1 topically was more effective at decreasing uveitis symptoms, including edema in the cornea and conjunctiva, hyperemia in the iris, and fibrin clots, when compared to the free enzyme." (PMID 37514137, 2023). "Other beneficial effects of SOD1 were obtained in the treatment of uveitis inflammation of the uveal tract involving both outer and inner structures of the eye." (PMID 33917028, 2021). "Topical Nano-SOD1 instillations showed high efficiency in decreasing uveitis manifestations, such as fibrin clots in the anterior chamber of the eye, corneal and conjunctival edema, and iris hyperemia." (PMID 33917028, 2021). "The ability of Nano-SOD1 to reduce inflammatory processes in the eye was examined in vivo in rabbits with a model immunogenic uveitis—the inflammation of the inner vascular tract of the eye." (PMID 33917028, 2021). "It is noteworthy that this nanoformulated SOD1 also appeared to be more effective than native SOD1 in the treatment of inflammatory eye disease, uveitis, just at topical instillations." (PMID 33917028, 2021). "It was shown during preclinical studies that topical instillations of Nano-SOD1 were much more effective compared to the free enzyme in decreasing uveitis manifestations." (PMID 33917028, 2021). "Clinical manifestations of uveitis in this group were less pronounced and appeared later than that in placebo- and SOD1-treated groups." (PMID 26697135, 2015). "The endogeneous SOD1 activity in aqueous humor of placebo-treated eyes with uveitis was increased by more than in 1.5 times compared to control group suggesting a compensatory reaction of the eye to the uveitis-induced oxidative stress." (PMID 26697135, 2015). "Still the decrease in the measured SOD1 activity in treated eyes clearly shows that SOD1 and, especially, nanozyme treatments decrease inflammation during experimental uveitis." (PMID 26697135, 2015). "We observed statistically significant differences in those clinical manifestations of uveitis, such as corneal and iris edema, hyperemia of conjunctiva, lens opacity, and amount of fibrin clots between this group and native SOD1-treated group." (PMID 26697135, 2015). "In this study, the therapeutic efficacy of SOD1 nanozyme for the treatment of ophthalmic inflammatory diseases was demonstrated in a rabbit model of immunogenic uveitis." (PMID 26697135, 2015). "In the second group of rabbits receiving native SOD1 solution, the clinical manifestations of uveitis were less severe." (PMID 26697135, 2015). "Previous studies have shown beneficial effects of SOD1 in the treatment of eye inflammation, including uveitis and eye burns." (PMID 26697135, 2015). "In the current study, we demonstrate the advantages of topical instillations of superoxide dismutase 1 in the form of “nanozyme” in the treatment of ocular inflammation in a rabbit model of immunogenic uveitis." (PMID 26697135, 2015). "The ability of SOD1 nanozyme as well as the native SOD1 to reduce inflammatory processes in the eye was examined in vivo in rabbits with immunogenic uveitis." (PMID 26697135, 2015). "The researchers tested the nano-SOD1 formulation in a uveitis rabbit model to reduce inflammation." (PMID 37514137, 2023). "Topical instillations of SOD1 at immunogenic uveitis induced by foreign animal serum resulted in the enhancement of general antioxidant activity in the eye and in the substantial decrease of leukocyte count in aqueous humor, even in comparison with dexamethasone." (PMID 33917028, 2021). "The SOD1-nanozyme appeared to be much more effective compared with the free enzyme in decreasing uveitis manifestations in rabbits, such as the intensity of corneal and iris edema, hyperemia of the conjunctiva, lens opacity, the amount of fibrin clots, and the protein content in aqueous humor." (PMID 34830247, 2021).
uveitis (continued). "Also, the experiments in vivo demonstrated a stronger anti-inflammatory effect of SOD1 included in calcium phosphate nanoparticles compared to native SOD1 in experimental immunogenic uveitis in rabbits." (PMID 34830247, 2021). "All these effects could in principle contribute to improved therapeutic effect of the SOD1 nanozyme during uveitis observed in this work." (PMID 26697135, 2015). "Thus, SOD1 was used for the treatment of lens-induced and bovine albumin-induced uveitis in rabbits, as well as for the treatment of acute corneal inflammation in animals induced by sodium hydroxide." (PMID 26697135, 2015). "Positive effect of SOD1 was also demonstrated on the rabbit model of immunogenic uveitis." (PMID 26697135, 2015). "Thus, while native SOD1 showed a pronounced therapeutic effect in the treatment of experimental immunogenic uveitis in rabbits, the nanoformulated form, SOD1 nanozyme, provided much more remarkable effect as revealed by the histopathology analysis." (PMID 26697135, 2015). "Topical instillations of SOD1-nanozyme significantly decreased inflammation both in the outer and inner parts of the eye as determined using scores of the clinical manifestations of uveitis, multiple biochemical parameters, and histological analysis." (PMID 26697135, 2015). "The development of uveitis also resulted in drastic increase of α2-macroglobulin activity in aqueous humor; however it was mitigated after both the native SOD1 and, especially, SOD1 nanozyme treatments." (PMID 26697135, 2015). "Thus, we demonstrated that nanozyme treatment resulted in the considerable improvement of uveitis condition in rabbits compared not only with the untreated animals but with the native SOD1-treated group as well." (PMID 26697135, 2015). "We have shown recently that SOD1 instillations may help to reduce clinical presentations of immunogenic uveitis in rabbits." (PMID 26697135, 2015). "Therefore a noninvasive topical SOD1 nanoformat that can be conveniently applied as eye drops by a patient if shown successful as a therapeutic modality could be a major breakthrough in treatment of uveitis and possibly other inflammatory conditions of the eye." (PMID 26697135, 2015). "Both SOD1 and glutathione peroxidase were employed for the treatment of severe experimental allergic uveitis induced by retinal S antigen in rats, while poly(ethylene glycol)- (PEG-) modified catalase and PEG-SOD were employed for the treatment of the same type of uveitis in guinea pigs." (PMID 26697135, 2015).
lung adenocarcinoma (9 papers, 2018 to 2025). A carcinoma that arises from the lung and is characterized by the presence of malignant glandular epithelial cells. "SOD1 expression was significantly higher in lung adenocarcinoma (ADC) and lung squamous cell carcinoma (SCC) than in normal tissues." (PMID 32391354, 2020). "With the increasing risk score of patients with lymph node metastasis of lung adenocarcinoma, the expression of high-risk mRNAs (HMMR, B4GALT1, ANGPTL4, EXT1, GPC1, RBCK1, SOD1, AGRN) was obviously upregulated." (PMID 31847905, 2019). "LCS-1 and SOD1 siRNAs inhibit the growth of LCS-1-sensitive lung adenocarcinoma cell lines." (PMID 29891006, 2018).
polycystic ovary syndrome (9 papers, 2019 to 2025). A disorder that manifests as multiple cysts on the ovaries. "We investigated the activity of the copper (Cu)-zinc (Zn) SOD1 as well as the level of Cu and Zn in the serum of women with polycystic ovary syndrome (PCOS) and control group." (PMID 35566673, 2022).
synucleinopathy (9 papers, 2013 to 2025). A neurodegenerative disease that is characterized by the abnormal accumulation of aggregates of alpha-synuclein protein in neurons, nerve fibers or glial cells. "Altogether, APP, CLU, CALCA, and SOD1 may contribute to the α-synuclein-associated synucleinopathy, whereas NEDD4 by posttranslational modification protects against the formation of toxic α-synuclein inclusions." (PMID 36523604, 2022). "Positive results in this paradigm establish an evidence-based foundation for examining synucleinopathy and aberrant SOD1 in human HIE brains." (PMID 40277911, 2025).